LATS2 (large tumor suppressor kinase 2)
Diseases named in the same sentence as LATS2 in open-access papers (continued):
Sharing a sentence is not in itself a finding about the gene and the disease.
nonalcoholic fatty liver disease (1 paper, 2017). "It was reported that Lats2 is crucial for cholesterol synthesis balance: Lats2 dysregulation is observed in some cases of nonalcoholic fatty liver disease (NAFLD)." (PMID 28467351, 2017).
oligodendroglioma (1 paper, 2021). A well-differentiated (WHO grade II), diffusely infiltrating neuroglial tumor, typically located in the cerebral hemispheres. "Inactivation of LATS1 and LATS2 would be associated with more aggressive tumours, and with a poorer prognosis, with the exception of oligodendrogliomas, for which hypermethylation of the LATS2 promoter predicts a better survival, as observed in CRC." (PMID 34885067, 2021).
pancreatic ductal adenocarcinoma (1 paper, 2025). An infiltrating adenocarcinoma that arises from the epithelial cells of the pancreas. "Furthermore, the deficiency of BAP1 triggers the ubiquitination and subsequent degradation of LATS2, ultimately culminating in the deregulation of the Hippo signaling pathway and the induction of pancreatic ductal adenocarcinoma in murine models." (PMID 40083694, 2025).
prostate tumor (1 paper, 2020). "They found out that miR-302/367 downregulated LATS2 expression and reduced the phosphorylation of YAP, and then resulted in enhanced YAP nuclear translocation in prostate tumor-propagating cells." (PMID 33414893, 2020).
psoriasis (1 paper, 2020). An autoimmune condition characterized by red, well-delineated plaques with silvery scales that are usually on the extensor surfaces and scalp. "Protein phosphatase 6 (PPP6C), which is inhibited by NF-κB activation and large tumor suppressor kinase 2 (LATS2), has been identified as a direct target of miR-31 in keratinocyte proliferation of psoriasis." (PMID 32806619, 2020).
pterygium (1 paper, 2016). A wedge-shaped fibrovascular lesion arising from the bulbar conjunctiva and extending to the cornea. "Therefore, silencing of LATS1 and LATS2 putative tumor suppressor genes through promoter methylation may cause the development of pterygium." (PMID 26942001, 2016). "Further studies are required to identify the exact molecular function of LATS1/LATS2 genes in pterygium in various and larger genetic populations using advanced molecular techniques." (PMID 26942001, 2016). "The data of this study is the first report regarding the effect of promoter methylation of the LATS1 and LATS2 in the pterygium." (PMID 26942001, 2016). "Promoter methylation of LATS1 and LATS2 was detected significantly between pterygium tissues and normal tissues [LATS1; OR = 4.9; 95% CI: 1.54 to 15.48, P = 0.003; LATS2; OR = 7.1; 95% CI: 1.53 to 33.19, P = 0.004]." (PMID 26942001, 2016).
serous ovarian carcinoma (1 paper, 2019). "The TCGA-RNASeqV2 data set showed that low LATS1 and LATS2 were associated with better survival in serous ovarian carcinoma." (PMID 31586262, 2019). "Despite heterogeneity among the different data sets, LATS expression is not an indicator of survival in serous ovarian cancer and LATS2 expression may even be tumorigenic." (PMID 31586262, 2019).
Splenomegaly (1 paper, 2024). Abnormal increased size of the spleen. "Our results demonstrate that loss of the LATS2 kinase endows bone ECs with disease-promoting properties, resulting in osteosclerotic defects, bone fibrosis, EMH and splenomegaly." (PMID 39155965, 2024).
systolic heart failure (1 paper, 2024). Heart failure caused by abnormal myocardial contraction during systole leading to defective cardiac emptying. "For example, forced expression of a constitutively active form of Yap in the adult heart stimulated cardiac regeneration and improves contractility after MI, while Hippo kinase pathway (Mst1, Lats2 and Mob1b) deficiency reversed systolic heart failure after MI." (PMID 38396885, 2024).
tumor (215 papers, 2007 to 2026). "Hippo signaling controlled the expression of genes of the MHC-I antigen processing and presentation pathway, and loss of LATS1 and LATS2, critical kinases required for Hippo signaling activation, favors tumor immune evasion through decreasing MHC-I expression." (PMID 39545415, 2024). "SEV miR-31-5p generated from tumor-associated macrophages (TAMs) can reduce the expression of the tumor suppressing gene LATS2 via disruption of the Hippo signaling cascade." (PMID 38243280, 2024). "A total of 6 LATS2 mutations occurred in approximately 6.1% (6/99) of the tumor specimens, including 1 truncating mutation, and 8 missense mutations." (PMID 38383447, 2024). "Among these genes from the Hippo signalling pathway, the DNA segments of the LATS2 promoter region were highly enriched; LATS2 encodes a vital serine/threonine protein kinase belonging to the large tumour suppressor family that influences mitosis initiation." (PMID 37553362, 2023). "LncRNA sSNHG17 knockdown or gefitinib treatment caused a remarkable upregulation of LATS2 in xenograft tumours tissues, while this effect was further strengthened by SNHG17 silencing and gefitinib co-treatment." (PMID 35902569, 2022). "Administration of a TERT inhibitor inhibited LATS2-mutated tumor growth in tumor-bearing mouse models." (PMID 36335095, 2022). "We discovered that LATS2 expression was negatively associated with tumor purity in COAD (r = −0.332, P = 6.23e−12) and READ (r = −0.384, P = 2.77e−6)." (PMID 34699318, 2021). "Next, the underlying relationships between LATS2 expression and tumor-infiltrating immune cells in CRC were investigated using the TIMER database." (PMID 34699318, 2021). "For example, showed that although inactivation of LATS1 and LATS2 led to enhanced anchorage-independent cell growth in vitro, it also caused increased tumor immunogenicity and tumor regression in vivo." (PMID 34150758, 2021). "Further studies are warranted to determine the underlying mechanisms for the correlations of LATS2 with tumor-infiltrating immune cells in CRC." (PMID 34699318, 2021). "We tested if deficiency in YAP1 phosphoregulation by LATS1/2 is sufficient to cause tumour formation by conditionally knocking out Lats1 and Lats2, in NEX-Cre lineage." (PMID 32404936, 2020). "LATS2 is a core kinase component of the Hippo tumor-suppressive signaling pathway that encodes a Ser/Thr protein kinase and LATS2-mediated YAP1 phosphorylation has been implicated in multiple human cancers." (PMID 32041942, 2020). "Loss of both Lats1 and Lats2, encoding potent tumour suppressors, leads to dramatic tissue overgrowth during gestation, revealing a function for these enzymes in restricting growth during pituitary development." (PMID 30912742, 2019). "It functions as a tumour suppressor and thus loss of LATS2 function is associated with many types of tumour such as soft tissue sarcomas, leukaemia and breast cancer." (PMID 31083564, 2019). "Together, these findings indicate that NF2 and LATS2 mutations can be coincident in a given MM tumor." (PMID 29565815, 2018). "The kinase activity of LATS2 has been implicated in negative regulation of Cyclin E/CDK2 in tumour suppression." (PMID 30046387, 2018). "Similar to Lats2 deletion, conditional knockout of Lats1 caused a significant increase in tumor burden relative to WT-PyMT littermate controls." (PMID 30456386, 2018). "No known oncogenes were found mutated, but four of the seven patients (GIST_150, _174, _124 and _188) showed deleterious mutations in two candidates (KEAP1 and LATS2) and in three well-known tumor suppressors (CDKN2A, CDKN1B and PTEN)." (PMID 26544626, 2015). "The pattern of equal distribution of LATS1/2 nonsense or frame-shift mutations is consistent with the idea that LATS1 and LATS2 are tumor suppressor genes." (PMID 25482410, 2015).
tumor (continued). "A novel missense mutation in LATS2 (R958H) was identified in both samples, affecting a highly conserved residue of the tumor suppressor protein." (PMID 25798586, 2015). "Activation of YAP/TAZ by loss of the Hippo pathway kinases Lats1 and Lats2 in tumor cells of different murine syngeneic tumor models of melanoma, head and neck carcinoma, and breast cancer enhanced anti-tumor immune responses that lead to cancer cell elimination." (PMID 38538573, 2024). "We explored whether the associations of LATS2 expression with gene markers for tumor-infiltrating immune cells were also present in other cancers." (PMID 34699318, 2021). "Notably, 3 tumours harboured deleterious mutations of the core Hippo pathway member LATS2, one tumour with a splicing mutation and 2 with missense mutations." (PMID 31959902, 2020). "As a member of the Hippo signaling pathway, the loss of LATS2 may destroy the Hippo signaling pathway and eventually lose its tumor-inhibiting function." (PMID 33268767, 2020). "In addition to NF2 mutations, genetic LATS2 inactivation is observed in MM cases, such that LATS2 inactivation, and its effects tumor suppression, were initially identified in seven of 20 MM cell lines analyzed in vitro." (PMID 29565815, 2018). "We then determined the mechanism underlying the tumor development effect of miR-31 and decreased whether LATS2 is involved in this process." (PMID 29145896, 2017). "Besides, in vivo experimentation revealed that DDX11‐AS1 exerted a facilitative effect on tumour development, while the expression of LATS2 mRNA displayed a substantial reduction within the tumour tissues and exhibited an inverse association with DDX11‐AS1 expression." (PMID 40387409, 2025). "This microRNA promotes tumor growth by targeting LATS2 (Large tumor suppressor kinase 2) and enhances invasiveness by inhibiting LZTS1 (Leucine zipper tumor suppressor 1)." (PMID 40399946, 2025). "In nasopharyngeal carcinoma, miR-424-5p facilitates cell growth, movement, and metastasis by targeting LATS2, a gene that suppresses tumor progression." (PMID 39866229, 2025). "For instance, the FDA-approved drug mitomycin C has been shown to upregulate LATS2 expression, induce cellular senescence, and suppress tumor progression in a mouse model of CC, demonstrating the feasibility of restoring this feedback loop pharmacologically." (PMID 41256331, 2025). "For instance, LINC01088 modulates the miR‐95/LATS2 pathway through a ceRNA mechanism, inhibiting tumour cell growth." (PMID 40000422, 2025). "First, small-molecule agents can be developed to enhance LATS2 activity or inhibit YAP1, thereby promoting LATS2 phosphorylation and reinstating its tumor-suppressive function." (PMID 41256331, 2025). "As a downstream kinase of the Hippo pathway,LATS2 is a tumor suppressor-modulating gene, and downregulation of LATS2 can promote the progression of different types of cancers." (PMID 40151143, 2025). "The authors found that miR-93 suppressed LATS2 expression and thereby enhanced tumor angiogenesis and metastasis." (PMID 37692482, 2024). "Subsequently, studies revealed that LATS2 is a tumor suppressor gene that controls cell proliferation, cell death, and cell migration." (PMID 38889502, 2024). "According to immunoblotting, lowered MELK and EZH2 expression and elevated LATS2 expression were observed in tumour tissues of nude mice injected with H1975 cells transduced with sh‐MELK." (PMID 38652219, 2024). "MELK expression remained unchanged, EZH2 expression decreased and LATS2 expression was augmented in tumour tissues of nude mice injected with H1975 cells transduced with sh‐EZH2." (PMID 38652219, 2024).
tumor (continued). "It has been documented that LATS2 is a widely recognized anti‐oncogene in numerous cancers by regulating tumour cell proliferation and apoptosis." (PMID 38652219, 2024). "AGAP2-AS1 is involved in cell migration and promotes tumorigenesis by suppressing the tumor suppressors LATS2 and KLF2." (PMID 37531393, 2023). "Our results showed that LEF1 recruits KDM4A and N-CoR, functioning in a coordinated manner to transcriptionally inhibit the tumour-suppressor gene LATS2 and promote OSCC progression." (PMID 37553362, 2023). "Previous experimental work in mice has shown that the LCD1 domain is critical for tumor suppressor activity of LATS2." (PMID 37728212, 2023). "NEX-Cre–mediated deletion of the other two members of the NDR kinase family, LATS1 and LATS2, causes YAP1 activation and tumour formation in brain." (PMID 36446521, 2023). "The expression of the indicated proteins in tumour specimens was analysed by WB, revealing higher LATS2 expression in the LEF1- or KDM4A-knockdown groups." (PMID 37553362, 2023). "LATS2, functioning as a tumour suppressor gene regulated by EZH2, was mutated in NSCLC, and overexpression of LATS2 induced cell apoptosis and inhibited NSCLC cell growth." (PMID 35379783, 2022). "As an important member of the LATS tumour inhibitor family, LATS2 has been reported to affect cellular homoeostasis, and low LATS2 expression has been found in various human cancers." (PMID 35902569, 2022). "To further explore the relationship between LATS2 and tumor immunity, we utilized CIBERSORT to assess immune infiltration." (PMID 36118851, 2022). "Subsequently, tumour volume and weight were confirmed based on xenograft nude mice models, Ki-67 and LATS2 expression was observed by immunohistochemistry." (PMID 33842488, 2021). "MiRNAs can combine with lncRNAs, such as MALAT1, to inhibit large tumor suppressor 2 (LATS2) to regulate the growth, invasion and metastasis of tumor cells." (PMID 34616746, 2021). "LATS2 is involved in immune-related pathway regulation and positively related to tumor-infiltrating immune cells." (PMID 34699318, 2021). "We further found that LATS2 was involved in the regulation of immune-related pathways and that its expression was positively related to tumor-infiltrating immune cells by GSEA, TIMER, and ssGSEA analyses." (PMID 34699318, 2021). "For example, LATS2 expression was reduced and negatively related to tumor size and metastasis in breast cancer." (PMID 34699318, 2021). "Low protein expression of LATS2 was clearly related to poor tumor differentiation, advanced TNM stage, and high T, N, and M stages in CRC." (PMID 34699318, 2021). "Taken with other Hippo pathway members (NF2, LATS1 and LATS2), 50% of tumours had at least one lesion of this pathway." (PMID 34580349, 2021). "In short, different signaling pathways inhibit the transcription and translation of LATS2 or the pathway regulated by LATS2 to exert tumor suppressor effect in various cancers." (PMID 34131399, 2021).
tumor (continued). "One pro-tumorigenic mechanism of hsa-miR-372 is through de-repression of the tumor suppressor LATS2, while repression of IGF2BP1 by hsa-miR-372 is a tumor-suppressive mechanism." (PMID 34600545, 2021). "LATS2 is a Dbf2-related kinase that acts as a central regulator of cell fate by regulating the function of numerous carcinogenic factors or tumor suppressor effectors." (PMID 34824999, 2021). "LATS2, as a potential tumor suppressor, is a significant mediator of the apoptosis response pathway." (PMID 33462260, 2021). "They showed that by deleting LATS1 and LATS2 (large tumor suppressor 1 and 2), tumor immunogenicity was modulated by enhancing the content of nucleic acid released in extracellular vesicles (EVs) by tumor cells." (PMID 34944765, 2021). "Low LATS2 expression was significantly related to tumor differentiation (P = 0.002), TNM stage (P = 0.002), primary tumor (T; P = 0.041), lymph node metastases (N; P = 0.012), and distant metastases (M; P = 0.006)." (PMID 34699318, 2021). "LATS2, a key component of the tumor-suppressive hippo signaling pathway, inhibits proliferation and promotes apoptosis by regulating yes-associated protein (YAP) activity." (PMID 33588913, 2021). "Previous work has demonstrated that LATS2 namely large tumor suppressor kinase 2 52, functions as a tumor suppressor effector, which has been reported in many cancers and its low expression was linked with advanced tumor progression." (PMID 34131399, 2021). "We demonstrated that YAP/TAZ signaling regulated by miR-429 promoted cell proliferation and tumor growth of COAD through targeting LATS2." (PMID 33414893, 2020). "Deletion of YAP1’s negative regulators LATS1 and LATS2 kinases in NEX-Cre lineage in double conditional knockout mice also generates similar tumours, which are rescued by deletion of YAP1 and its paralog TAZ." (PMID 32404936, 2020). "LATS2, a core kinase of the Hippo tumor-suppressing signaling pathway, was shown to be underexpressed in OSCC cells and a direct target of miR-31." (PMID 33230440, 2020). "Our findings demonstrated the roles of circ_0000140 in OSCC tumorigenesis as well as in metastasis, and circ_0000140 exerts its tumor-suppressing effect through miR-31/LATS2 axis of Hippo signaling pathway in OSCC." (PMID 32041942, 2020). "Taken together, these results suggest that the tumor-suppressive effects of the LATS2-JNK pathway are likely due to both the induction of mitochondrial fragmentation and disruption of mitochondrial turnover." (PMID 32554853, 2020). "Both LATS1 and LATS2, are deregulated in various human cancers and correlate with tumor progression." (PMID 31391070, 2019). "Large tumor suppressor (LATS) family proteins LATS1 and LATS2 have been proposed to be tumor suppressors." (PMID 31586262, 2019). "In this mechanism, the upregulated expression of FOXC1 leads to expression of the miR-31-5p transcript, which induces cell proliferation by suppressing the expression of an anti-tumor gene, LATS2." (PMID 31623173, 2019). "In line with this, we reveal a mechanism by which FOXC1 is related to chemoresistance and promotes tumor growth via the miR-31-5p/LATS2 pathway." (PMID 31623173, 2019). "It has also reported that the miR-93 can be involved in tumor metastasis through repressing LATS2 and p21 expression." (PMID 31470870, 2019).